S100A12 (S100 calcium binding protein A12)
Diseases named in the same sentence as S100A12 in open-access papers (continued):
Sharing a sentence is not in itself a finding about the gene and the disease.
leprosy (6 papers, 2016 to 2025). Leprosy is a chronic infectious disease affecting primarily the skin and peripheral nervous system. "High αPGL-I IgM, IP-10, and CRP levels, relative to controls, were associated with MB leprosy, whereas ApoA1 and S100A12 levels were critical for identification of both patients groups." (PMID 33490914, 2021). "The levels of CCL4 and S100A12 showed a significant result in both the correlation and cross-sectional analysis, indicating an association of these markers with leprosy and/or M. leprae infection among HCs." (PMID 32849645, 2020). "Recently, a multi-biomarker test (MBT) evaluating αPGL-I IgM, IP-10, CRP, S100A12, and ApoA1 was successfully used to discriminate patients with MB and PB leprosy from control individuals in high and low leprosy endemic areas." (PMID 35416839, 2022). "A host biomarker signature of αPGL-I IgM, IP-10, CRP, ApoA1, and S100A12 was identified, covering both the humoral and cellular pole of the immunopathologic leprosy spectrum." (PMID 33490914, 2021). "In contrast to our findings in Bangladesh, R values of S100A12 in contacts and patients with PB leprosy were similar to those of healthy controls in South Korea." (PMID 33490914, 2021). "As previously demonstrated, S100A12 also remained a useful marker to discriminate leprosy patients from EC." (PMID 32849645, 2020). "Protein levels of S100A12 have been previously reported in patients with leprosy, however, the role of S100A12 in macrophage antimicrobial activity against intracellular pathogens, including mycobacteria, has not been investigated." (PMID 27355424, 2016). "In contrast to our results, S100A12 has been previously reported to be equally present in lesions from patients with the different clinical forms of leprosy." (PMID 27355424, 2016). "At the site of disease in leprosy, we found that S100A12 was more strongly expressed in skin lesions from tuberculoid leprosy (T-lep), the self-limiting form of the disease, compared to lepromatous leprosy (L-lep), the progressive form of the disease." (PMID 27355424, 2016). "By studying leprosy as a model, we found that expression of S100A12 was greater in skin lesions from patients with the self-limiting versus the progressive form of the disease." (PMID 27355424, 2016). "RR specimens also expressed S100A12, which encodes an antimicrobial protein induced by TLR2/1L and IFN-γ in human macrophages, as well as IL12B and IL12RB2, known to be involved in host defense against leprosy." (PMID 40569678, 2025). "S100A12 thus seems to protect exposed individuals from M. leprae colonization and infection, but once infected, S100A12 can contribute to maintain a detrimental, pro-inflammatory state in leprosy patients." (PMID 32849645, 2020).
ulcerative colitis (6 papers, 2010 to 2023). An inflammatory bowel disease involving the mucosal surface of the large intestine and rectum. "As in our previously conducted study, we assessed the levels of pro-GN, PTX3 and S100A12 in serum of patients with ulcerative colitis, and we also compared the profiles of these biomarkers among patients with CD and UC." (PMID 37892129, 2023). "In our previous study, we assessed the serum profiles of pro-GN, PTX3 and S100A12 protein in patients with ulcerative colitis." (PMID 37892129, 2023). "In comparison to our previous research conducted on a group of patients with ulcerative colitis (UC), those with CD exhibited reduced levels of PTX3 (2117.9 vs. 3197.05, p < 0.005) and elevated concentrations of S100A12 (79.4 vs. 39.36, p < 0.05)." (PMID 37892129, 2023).
vasculitis (6 papers, 2009 to 2026). "We analyzed the cohort of 138 RA patients for associations between serum levels of S100A9, S100A8, S100A12 and sRAGE with RA clinical variables, CV risk factors, and with complications such as vasculitis, radiographic changes, and CV events." (PMID 19284577, 2009). "In conclusion, the serum and urine levels of S100A8/A9 and S100A12 in patients with active MPO-ANCA-positive vasculitis were elevated and correlated with the severity of the disease." (PMID 36088289, 2022). "In the current study, we tried to investigate the role of S100A8/A9 and S100A12 in MPO-ANCA-positive vasculitis." (PMID 36088289, 2022). "The raised levels of complement factors in the supernatant and the increased C5 expression of ANCA-activated neutrophils demonstrated that S100A8/A9 and S100A12 could promote the activation of the alternative complement pathway in MPO-ANCA-positive vasculitis." (PMID 36088289, 2022). "S100A12 levels are known to increase in cases of infection, malignancy, and vasculitis." (PMID 33576586, 2021). "Besides, S100A12 could promote vasculitis by stimulating the production of IL-1β, which directly induces CA endothelial cell dysfunction and impacts the risk of the formation of CAL in children with KD." (PMID 36829193, 2023). "Original human studies investigating S100A8/9, S100A12, S100A4, and S100A10 in any form of vasculitis or related vascular inflammation were included." (PMID 41958648, 2026). "We and others previously established that S100 calcium-binding protein A12 (calgranulin C, S100A12), an intrinsic protein released by activated neutrophils, is a reliable marker of systemic inflammation that tracks with disease activity in an acute form of childhood vasculitis." (PMID 30533405, 2018). "The observed elevation in PMN and S100A12 in patients with PR3-AAV and, to a lesser extent, ANCA-negative vasculitis affecting small to medium vessels, was not attributable to higher disease activity in these individuals." (PMID 30533405, 2018).
acute myocardial infarction (5 papers, 2018 to 2024). Necrosis of the myocardium, as a result of interruption of the blood supply to the area. "A potential role of S100A12 in mediating plaque instability or acute myocardial infarction is supported by epidemiological data." (PMID 30467547, 2018). "Literature retrieval results uncovered that the interaction between hubgenes (VNN2, S100A12) and acute myocardial infarction has not been well established previously." (PMID 35722095, 2022).
colorectal cancer (5 papers, 2014 to 2021). A primary or metastatic malignant neoplasm that affects the colon or rectum. "S100A5 protein was also found in colorectal cancer cell lines, and S100A12 protein was found in EVs from brain cancer cells, colorectal cancer cells, melanoma cells, kidney cancer cells and more." (PMID 34721407, 2021). "In conclusion, during laparoscopic colectomy in patients with colorectal cancer, the peak airway pressure, the incidence of postoperative respiratory complications, and plasma sRAGE and S100A12 levels were lower in the PCV group than in the VCV group." (PMID 31740727, 2019). "Its reported function involves calcium regulation and arachidonic acid metabolism in the neutrophile granulocytes; it has also been reported that the expression of S100A12 was up-regulated both at mRNA and protein levels in the patients with colorectal carcinoma relative to healthy volunteers." (PMID 24839399, 2014).
irritable bowel syndrome (5 papers, 2010 to 2025). Irritable bowel syndrome (IBS) is a chronic functional condition of the lower gastrointestinal (GI) tract characterized by abdominal pain or discomfort and disordered bowel habit (diarrhea, constipation, or fluctuation between the two). "In addition, studies have shown that the concentration of S100A12 is elevated in people with irritable bowel syndrome (IBS)." (PMID 29991970, 2018). "When measured in stool, some studies have shown that S100A12 has higher sensitivity and specificity for distinguishing IBD from irritable bowel syndrome (IBS) than fecal calprotectin or lactoferrin." (PMID 34362144, 2021). "In this study, the utility of serum S100A12, in discriminating IBD from irritable bowel syndrome (IBS), was tested." (PMID 20946669, 2010).
pneumonia (5 papers, 2012 to 2025). An acute, acute and chronic, or chronic inflammation focally or diffusely affecting the lung parenchyma, caused by an infection in one or both of the lungs (by bacteria, viruses, fungi, or mycoplasma.). "The frequency of MDSCs and effectors, including arginase-1, S100A8/A9, and S100A12, were significantly increased in the pneumonia group compared with the stable group." (PMID 35242775, 2022). "The percentage of MDSCs in PBMCs and the representative effectors, including Arg-1, S100A8/A9 and S100A12, were compared between the pneumonia group and the stable group." (PMID 35242775, 2022). "All the MDSC effectors detected were much higher in the pneumonia group, especially S100A12, which showed an order of magnitude difference (171.7, IQR 77.7–704.1 vs. 0.007, IQR 0.002–0.013, p < 0.001)." (PMID 35242775, 2022).
chronic kidney disease (4 papers, 2017 to 2025). Impairment of the renal function secondary to chronic kidney damage persisting for three or more months. "It has also been shown that in patients with end-stage renal disease, there is a positive correlation between S100A12 levels and the risk of PAD." (PMID 40269701, 2025). "Moreover, in patients with end stage renal disease on hemodialysis, circulating S100A12 levels are associated with cardiovascular mortality, progression of abdominal aortic calcification and with progression of CAC." (PMID 30467547, 2018).
chronic obstructive pulmonary disease (4 papers, 2015 to 2021). A chronic and progressive lung disorder characterized by the loss of elasticity of the bronchial tree and the air sacs, destruction of the air sacs wall, thickening of the bronchial wall, and mucous accumulation in the bronchial tree. "Additionally, S100A12 produces secreted mucin 5AC (MUC5AC) from airway epithelial cells, which is related to an increased intracellular mucin production that could predispose e-cigarette users to airway obstruction similar to chronic obstructive pulmonary disease patients." (PMID 33924379, 2021).
endometriosis (4 papers, 2018 to 2024). The growth of functional endometrial tissue in anatomic sites outside the uterine body. "S100A12 serum protein has also shown some promise as a blood biomarker for the non-invasive diagnosis of endometriosis." (PMID 39684780, 2024). "Higher mRNA and protein levels of S100A12 were detected in primary endometrial stromal cells (ESCs) isolated from ectopic endometrium (lesions) of patients with endometriosis compared to ESCs isolated from the endometrium of healthy women." (PMID 39684780, 2024). "Additionally, the expression of RAGE and EN-RAGE, the downstream effectors of S100A12, was significantly increased, as evidenced by the significantly greater mRNA and protein expression in the cells of the endometriosis patients." (PMID 30558666, 2018). "Several members of the S100 protein family were under-expressed in the eutopic endometrium of women with endometriosis during the mid-secretory phase: S100A7, S100A8, S100A9, and S100A12." (PMID 35204508, 2022). "The combination of JUP with S100A12 in contrast did not add any benefit to the endometriosis diagnosis compared to JUP." (PMID 39684780, 2024).
gastritis (4 papers, 2012 to 2025). Inflammation of the stomach. "Quantification of these differences found significantly more S100A12-positive cells in the gastric mucosa of H. pylori+/gastritis+children when compared to group 2 and group 3." (PMID 32184815, 2020). "This study also reported a direct correlation between S100A12-positive cells and gastritis scores, linking S100A12 expression to inflammation of gastric mucosa infected with H. pylori." (PMID 32184815, 2020). "Serial formalin-fixed, paraffin-embedded sections of antral biopsies were stained for S100 proteins A8, A9, and S100A12; results showed that children have normal gastric mucosa (group 2) or were negative for H. pylori, but had gastritis (group 3) and had very few S100-positive cells." (PMID 32184815, 2020).
heart failure (4 papers, 2022 to 2025). Inability of the heart to pump blood at an adequate rate to meet tissue metabolic requirements. "Previous studies have linked S100A12 to various cardiovascular diseases, including heart failure, ST-elevation myocardial infarction (STEMI), and coronary artery disease (CAD)." (PMID 40926894, 2025).
lung carcinoma (4 papers, 2018 to 2025). "For instance, S100A12 generally shows low expression in lung cancer, while S100A7 is more specific to squamous and large cell carcinomas, but not adenocarcinomas or small cell lung cancer." (PMID 40735471, 2025). "S100A12, a member of the calgranulin protein family, is related to innate immunity and has been proposed as a prognostic factor in GC, while F13A1 has been associated with tumor metastasis in lung cancer and poor prognosis in several cancers." (PMID 41155404, 2025). "However, the roles of S100A1, S100A3, S100A7A, S100A12, S10016, and S100G proteins in lung cancer are rarely reported." (PMID 29607329, 2018).
lung diseases (4 papers, 2012 to 2023). "Therefore, we are not sure whether the sRAGE and S100A12 changes would be the same in the presence of previous lung diseases." (PMID 22616947, 2012).
oropharyngeal squamous cell carcinoma (4 papers, 2016 to 2020). "It has been reported that high levels of S100A12 has been correlated with good prognosis for patients with oropharyngeal squamous cell carcinoma." (PMID 32228516, 2020). "The present study was in line with the earlier study on the expression of S100A12, which was highly correlated with the prognosis and high survival rates of oropharyngeal squamous cell carcinoma patients." (PMID 32228516, 2020). "For S100A12, high level in tumor tissue is a good prognostic indicator for oropharyngeal squamous cell carcinoma patient." (PMID 27297407, 2016). "In oropharyngeal squamous cell carcinoma, S100A12 in addition to S100A8 and S100A9 was downregulated as observed by IHC; simultaneous reduction in both S100A8 and S100A12 expression was associated with worse overall patient survival." (PMID 26883112, 2016). "Moreover, high expression of S100A8 and S100A12 has a positive prognostic impact on oropharyngeal squamous cell carcinoma." (PMID 32211332, 2020).
periodontal disease (4 papers, 2020 to 2025). "Notably, S100A12, a multifunctional protein implicated in smoking-related pathologies, allergic asthma, and periodontal diseases, plays a critical role in regulating immune responses, chemotaxis, intracellular signaling, and oxidative stress." (PMID 39819313, 2025). "It has been shown that S100A12 levels in saliva are associated with periodontal disease." (PMID 32082330, 2020). "Four studies identified that the presence of IBD and periodontal disease was associated with higher levels of prostaglandin E2, aMMP8, IL-18 and S100A12, respectively, when compared to patients without the coexistence of both diseases." (PMID 34501547, 2021). "Lastly, the levels of S100A12 in saliva from a large cohort of orally examined participants (n = 336) were measured to investigate whether S100A12 is a potential biomarker for periodontal disease." (PMID 32082330, 2020).
peripheral arterial disease (4 papers, 2016 to 2025). A disorder of the arteries supplying the upper and lower extremity and the visceral organs. "In another study, the S100A12 level had a positive independent association with peripheral arterial disease in 152 HD patients." (PMID 26914918, 2016). "The association between S100A12 and risk of peripheral arterial disease remains unclear." (PMID 40269701, 2025). "Based on the results from selecting hub genes among 15 potential candidate genes, four hub genes were selected that were significantly upregulated in both CD and peripheral arterial disease: S100A8, S100A9, S100A12, and CXCR2." (PMID 40422241, 2025). "The pathways associated with neutrophil activation, chemotaxis, and migration were significantly correlated with the high expression of S100A8, S100A9, S100A12, and CXCR2 in CD and peripheral arterial disease." (PMID 40422241, 2025).
psoriatic arthritis (4 papers, 2006 to 2025). Joint inflammation associated with psoriasis. "However, other studies have revealed that high baseline S100A12 concentration is associated with higher disease activity and response to methotrexate (MTX) and anti-TNF therapy in patients with JIA including pJIA, ERA, oligoarticular and psoriatic arthritis." (PMID 34425842, 2021). "This study evaluated a synthetic KYNA analog’s effects on TNF-α, S100A8/9, S100A12, α-defensin, and interleukin-17 (IL-17) production and TSG-6 expression in ankylosing spondylitis (AS) and psoriatic arthritis (PsA)." (PMID 41465233, 2025).
respiratory distress syndrome (4 papers, 2012 to 2025). "Data shows that S100A12 is elevated in bronchoalveolar fluid of patients with asthma and respiratory distress syndrome (RDS)." (PMID 22811950, 2012).
uveitis (4 papers, 2018 to 2024). An inflammatory process affecting a part of or the entire uvea. "Furthermore, serum levels of both S100A8/A9 and S100A12 correlate with uveitis activity." (PMID 34438537, 2021). "S100A8/A9 heterodimers and S100A12 are elevated in both serum and AqH in JIA-associated uveitis patients as compared to JIA patients without uveitis." (PMID 34438537, 2021).
acute kidney injury (3 papers, 2022 to 2026). Sudden and sustained deterioration of the kidney function characterized by decreased glomerular filtration rate, increased serum creatinine or oliguria. "In addition, since mortality was associated with acute renal failure and shock, the plasma levels of AGE, sRAGE, HMGB1, and S100A12 were used to analyze the presence and absence of acute renal failure and shock." (PMID 35723375, 2022).
carotid atherosclerosis (3 papers, 2013 to 2023). A thickening and loss of elasticity of the walls of carotid arteries that occur with formation of atherosclerotic plaques. "In human, several S100 proteins, including S100A7, S100A8, S100A9, and S100A12, are linked with the severity of coronary and carotid atherosclerosis." (PMID 30886860, 2019). "Clinical data show positive correlations between S100A12 and the severity of coronary and carotid atherosclerosis." (PMID 38275751, 2023). "Clinical data show clear correlations between S100A12 and the severity of coronary and carotid atherosclerosis, but mechanistic studies on the role of S100A12 in CVD are hampered by the absence of this protein in mice." (PMID 24453429, 2013).
corneal infection (3 papers, 2019 to 2024). A viral or bacterial infectious process affecting the cornea. "We also showed S100A12 to be effective in inhibiting F. solani corneal infections in vivo with significant reduction of corneal opacity and fungal burden in infected corneas treated with S100A12 compared with untreated ones." (PMID 38301897, 2024). "We determined the expression pattern of AMPs elicited in corneal infections caused by S. pneumoniae in patients for the first time, and we found significantly increased expressions of hBD2 and 3, S100A8, S100A9, S100A12, LL-37, lipocalin, Rnase7, and hepcidin." (PMID 30845777, 2019). "In our earlier study we investigated the expression of AMPs from corneal scrapings of patients with P. aeruginosa corneal infections and saw differential expression of several AMPs, including human β defensins (hBD) 2, and 3, S100A9, S100A12 and LL-37." (PMID 32507000, 2020).